ACSS3 (acyl-CoA synthetase short chain family member 3)
Description:
Catalyzes the synthesis of acetyl-CoA from short-chain fatty acids. Propionate is the preferred substrate. Can utilize acetate and butyrate with a much lower affinity (By similarity).
Synonyms: FLJ21963
Tractability: PROTAC: its protein half-life has been measured.
Gene: Protein-coding gene on chromosome 12 (80,936,414 to 81,261,210, forward strand). Ensembl gene ENSG00000111058.
Subcellular location: Mitochondrion matrix
Subcellular location (Human Protein Atlas): Mitochondria
Pathways (Reactome):
Gene expression (Transcription): MLL4 and MLL3 complexes regulate expression of PPARG target genes in adipogenesis and hepatic steatosis
Metabolism: Synthesis of Ketone Bodies
Gene Ontology:
Molecular function: propionate-CoA ligase activity; protein binding; acetate-CoA ligase activity; medium-chain fatty acid-CoA ligase activity; short-chain fatty acid-CoA ligase activity
Biological process: ketone body biosynthetic process
Cellular component: mitochondrial matrix; mitochondrion
Genetic constraint (gnomAD): Loss-of-function variants: 55 observed, 73.95 expected, observed/expected ratio (o/e) 0.74, 90% interval 0.6 to 0.93. The upper end of that interval is the gene's LOEUF score, 0.93, which puts it in group 3 of 6, group 1 being the genes least tolerant of losing a copy. Missense variants: 744 observed, 816.95 expected, observed/expected ratio (o/e) 0.91, 90% interval 0.86 to 0.97. Synonymous variants: 302 observed, 293.93 expected, observed/expected ratio (o/e) 1.03, 90% interval 0.93 to 1.13.
Homologues: Orthologues: chimpanzee ACSS3 (99% identical), macaque ACSS3 (98% identical), dog ACSS3 (91% identical), rabbit ACSS3 (91% identical), rat Acss3 (91% identical), mouse Acss3 (90% identical), pig ACSS3 (88% identical), guinea pig ACSS3 (84% identical), tropical clawed frog acss3 (69% identical), zebrafish acss3 (64% identical), Drosophila melanogaster CG6432 (43% identical). Paralogues in human: ACSS2 (33% identical), ACSS1 (32% identical), ACSM3 (21% identical), ACSM2A (21% identical), ACSM1 (21% identical), ACSM2B (20% identical), ACSM4 (20% identical), ACSM5 (20% identical), AACS (18% identical), ACSF2 (15% identical), ACSM6 (15% identical), ACSF3 (14% identical), and 1 more.
Diseases named in the same sentence as ACSS3 in open-access papers:
ACSS3 is named in the same sentence as 22 diseases in open-access papers, as found by Europe PMC text mining. Sharing a sentence is not in itself a finding about the gene and the disease. The quoted sentences say what the papers report.
prostate carcinoma (6 papers, 2021 to 2025). A carcinoma that arises from epithelial cells of the prostate gland. "ACSS3 was also found to downregulated and associated with poor prognosis in prostate cancer." (PMID 35685372, 2022). "Collectively, these results indicated that ACSS3 was downregulated and predicted poor prognosis in prostate cancer." (PMID 33391508, 2021). "Together, these results establish ACSS3 inhibits prostate cancer progression and new endocrine therapy resistance by reducing intratumoral lipid accumulation." (PMID 33391508, 2021). "Acyl-CoA synthetase short chain family member 3 (ACSS3) is a protein that represses prostate cancer progression, decreases fatty acid oxidation, enhances anaerobic glycolysis, increases Reactive Oxygen Species production, suppresses mitophagy, and promotes apoptosis." (PMID 41302034, 2025). "ACSS3 is a metabolic enzyme in charge of catalyzing the synthesis of acetyl coenzyme A from short-chain fatty acids, which corresponds with the progression of gastric, hepatocellular, bladder, and prostate cancers." (PMID 36081667, 2022). "upregulation of ACSS3 in prostate cancer cells regulates PLIN3 stability, reduces lipid droplet deposition, and induces ER stress-mediated apoptosis, reversing enzalutamide resistance and hindering castration-resistant prostate cancer progression." (PMID 41145471, 2025). "We used PC3 cells to detect the effect of ACSS3 in AR negative prostate cancer, and the results showed that ACSS3 could also inhibit the proliferation of PC3 cells." (PMID 33391508, 2021).
gastric cancer (2 papers, 2022). A primary or metastatic malignant neoplasm involving the stomach. "Whilst upregulated ACSS3 expression in gastric cancer was correlated with the tumour proliferation and invasion." (PMID 35685372, 2022). "To date, most of the studies on ACSS3 focus on its oncogenic role in human tumours, including gastric cancer, hepatocellular carcinoma and bladder cancer." (PMID 35184387, 2022).
Glucose intolerance (1 paper, 2022). Glucose intolerance (GI) can be defined as dysglycemia that comprises both prediabetes and diabetes. "Knockout of Acss3 gene (Acss3–/–) in mice reduces brown adipose tissue (BAT) mass but increases white adipose tissue (WAT) mass, leading to glucose intolerance and insulin resistance that are exacerbated by high‐fat diet (HFD)." (PMID 35184387, 2022).
Hepatic steatosis (1 paper, 2022). Steatosis is a term used to denote lipid accumulation within hepatocytes. "Pharmacologically inhibition of autophagy by HCQ/wortmannin inhibits propionate‐induced autophagy in vitro, and HCQ treatment ameliorates obesity, hepatic steatosis and insulin resistance of the Acss3–/– mice in vivo." (PMID 35184387, 2022). "The elevated levels of propionate in Acss3–/– mice similarly drive adipocyte autophagy, and pharmacological inhibition of autophagy using hydroxychloroquine ameliorates obesity, hepatic steatosis and insulin resistance of the Acss3–/– mice." (PMID 35184387, 2022). "Pharmacological inhibition of autophagy by HCQ ameliorates obesity, hyperlipidaemia, hepatic steatosis and insulin resistance phenotypes in Acss3–/– mice." (PMID 35184387, 2022). "Collectively, HCQ treatment inhibits fat accumulation in Acss3 KO mice and ameliorates their metabolic dysfunctions and hepatic steatosis." (PMID 35184387, 2022).
Immunodeficiency (1 paper, 2022). Failure of the immune system to protect the body adequately from infection, due to the absence or insufficiency of some component process or substance. "ITGB2 plays a vital role in immune response, silencing ITGB2 leads to leukocyte adhesion deficiency and IRF7 is associated with immunodeficiency, enhanced expression of ACSS3 will help the migrated cells to evade from the immune elimination." (PMID 35685372, 2022).
Impaired glucose tolerance (1 paper, 2022). An abnormal resistance to glucose, i.e., a reduction in the ability to maintain glucose levels in the blood stream within normal limits following oral or intravenous administration of glucose. "The impaired glucose tolerance of Acss3–/– mice was also improved by HCQ treatment, though not significant (p = 0.09)." (PMID 35184387, 2022).
Insulin resistance (1 paper, 2022). Increased resistance towards insulin, that is, diminished effectiveness of insulin in reducing blood glucose levels. "The increased serum propionate levels and associated obesity and insulin resistance of the Acss3–/– mice prompted us to examine if higher serum propionate concentration was correlated to obesity and T2D in humans." (PMID 35184387, 2022). "Our study for the first time reveals the physiological function of ACSS3 in vivo and identifies an essential role of Acss3 in propionate metabolism, adipocytes autophagy, obese and insulin resistance." (PMID 35184387, 2022). "Using a novel Acss3–/– mouse model, we further show that deletion of Acss3 reduces BAT mass and increases WAT mass, elevates autophagy and promotes lipid accumulation in adipocytes, leading to insulin resistance and systemic metabolic syndrome." (PMID 35184387, 2022).
melanoma (1 paper, 2020). A malignant, usually aggressive tumor composed of atypical, neoplastic melanocytes. "Transfected conjunctival melanoma cells overexpressing mutant ACSS3 showed higher proliferative activity, supporting the direct involvement of this gene in the tumorigenesis of CJM." (PMID 33383577, 2020).
Obesity (1 paper, 2022). Accumulation of substantial excess body fat. "Specifically, we found that Acss3 KO caused an obesity‐like phenotype in mice with increased fat mass but smaller BAT." (PMID 35184387, 2022). "To further establish whether ACSS3 level is correlated to obesity and T2D, we retrieved data from published studies, in which ACSS3 expressions in WAT from lean and obese patients, as well as insulin sensitive and insulin‐resistant patients are available." (PMID 35184387, 2022).
renal carcinoma (1 paper, 2024). A carcinoma arising from the epithelium of the renal parenchyma or the renal pelvis. "The association of ACSS3 with sex or survival has not been reported in renal cancer, but it has been studied in other cancers." (PMID 38982123, 2024).
cancer (10 papers, 2017 to 2024). A tumor composed of atypical neoplastic, often pleomorphic cells that invade other tissues. "ACSS1 was associated with iHCC3, which had the lowest survival rate, whereas ACSS2 was associated with the moderate survival rate cancers (iHCC2) and ACSS3 was associated with the subtype having the longest patient survival rate (iHCC1)." (PMID 33304273, 2020). "The few studies available in the literature suggest that ACSS3 is a propionyl‐CoA synthetase and plays a role in cancer cell growth." (PMID 35184387, 2022). "The publicly available Cancer Cell Line Encyclopedia (CCLE) database was used for bioinformatic analyses to evaluate the methylation status of the ACSS3 promoter in different PCa cell lines." (PMID 33391508, 2021). "We found that the average methylation level of CpG sites located in CpG islands within the promoter regions of ADHFE1 and ACSS3 were significantly increased in cancer samples compared to normal samples (∆mBVs = 0.2 and 0.18, respectively)." (PMID 32317010, 2020). "In this study, we determined that ACSS3 is a landmark of cancer progression gatekeeper gene in GCa patients, which is part of the biochemical process for the mitochondrial production of acetyl‐CoA." (PMID 29493120, 2018). "The results revealed an adaptation mechanism where mitochondrial ACSS3 can resupply acetyl‐CoA for cancer cells to escape aerobic stress." (PMID 29493120, 2018). "Moreover, the Acyl-CoA Synthetase Short Chain Family Member 3 (ACSS3) is recognized as a crucial regulator of cancer cell metabolism, especially in the context of metabolic stress." (PMID 37310469, 2023). "Our observations for the first time extended the function of ACSS3 beyond cancer cells." (PMID 35184387, 2022). "However, in cancer cells, another mitochondrial-active enzyme, acetyl-CoA synthetase 3 (ACSS3), is overexpressed." (PMID 33919178, 2021). "This is the first report, surprisingly, revealed ACSS3 as important cancer prognosis biomarker." (PMID 29493120, 2018). "Furthermore, in vitro study revealed that ACSS3 is critical for cancer cell growth, migration, and death under starvation conditions." (PMID 29493120, 2018). "Therefore, it is very likely that the C/EBPα‐ACSS3 axis is an important regulatory mechanism in GCa development or when cancer cells are under energy deprivation stress." (PMID 29493120, 2018). "The mitochondrial forms, ACSS1 and ACSS3, most likely play a significant role in energy derivation via oxidation of acetate and propionate, respectively, but may be less involved in regulatory functions in cancer cells than ACSS2." (PMID 33304273, 2020). "Targeting ACSS3 could be a novel therapeutic strategy for cancer, in this case, GCa." (PMID 29493120, 2018). "In addition to its role as an acetyl‐CoA provider in GCa cells, ACSS3 might also inhibit cancer autophagic activity and escape autophagocide." (PMID 29493120, 2018). "FAS, C16orfS4, FBXO31, ACSS3, ZCCHC8 and THBS3 were found to help the metastatic cancer cells survive from the immune surveillance." (PMID 35685372, 2022). "IPA enrichment analysis of hyper-DMRs identified in very early stage cancers selected Ethanol degradation II as the top term for functional impact, in which ADHFE1 and ACSS3 were hit." (PMID 32317010, 2020). "These discrepancies will have to be reconciled by future studies that demonstrate whether ACSS3 can indeed utilize acetate at concentrations and conditions found in the mitochondrial matrix, and that ACSS1 is not the preferred route in some cancers." (PMID 33304273, 2020).
tumor (10 papers, 2014 to 2025). "Comparative analysis of TIL-generating (TIL+) versus non-generating (TIL-) tumors revealed that IL7Rexpression, structured perivascular immune clustering, and tumor-intrinsic metabolic programs such as ACSS3 were associated with successful TIL expansion." (PMID 40313763, 2025). "In the PPI results, we observed that molecules such as MAPK14, ATP6V1, Itgbs, MB2, STAT3, PKM, ACSS3, and MYL9, which are associated with signal transduction, inflammation, and tumor invasion, exhibited more active interactions with other molecules." (PMID 38203782, 2024). "High PLIN3 expression was negatively correlated with ACSS3 expression and positively correlated with tumor stage and Gleason score." (PMID 33391508, 2021). "In the current study, we found that ACSS3/PLIN3-mediated LD elimination significantly reduced lipid/cholesterol contents in tumor cells, thus repressing intratumoral androgen synthesis, thereby inhibiting CRPC progression and Enzalutamide resistance." (PMID 33391508, 2021). "The results showed that ACSS3 inhibited cell proliferation and migration, decreased LD deposit size and promoted ER stress, and the ACSS3-mediated tumor cell suppression function was mediated through downregulation of PLIN3." (PMID 33391508, 2021). "In agreement with the prognostic characteristics of the ACSS1 and ACSS2 enzymes it was seen in HCC subtype-specific GEMs that iHCC1 tumours favourably expressed ACSS2, iHCC2 tumours ACSS3, whereas iHCC3 tumours ACSS1 for acetate utilisation." (PMID 32201876, 2021). "Here, we demonstrated that restoration of ACSS3 expression in PCa cells significantly reduced LD deposits, which increased ER stress-mediated apoptosis, thus inhibiting tumor growth and metastasis." (PMID 33391508, 2021). "Then compared with overexpressed PLIN3, overexpressed ACSS3+PLIN3 did not affect cell proliferation, migration, LD deposition area, TG and cholesterol content, indicted that PLIN3 rescued the ACSS3-mediated tumor cell suppression function." (PMID 33391508, 2021). "ACSS3 inhibited tumor growth and metastasis in the presence of endogenous PLIN3, while the effects of ACSS3 expression was mediated through downregulation of PLIN3." (PMID 33391508, 2021). "Next, according to an in-depth analysis of the TCGA and Taylor databases, we found that low ACSS3 expression was positively correlated with tumor stage, metastasis, recurrence and Gleason score and served as an independent prognostic factor." (PMID 33391508, 2021). "Taken together, these results indicated that ACSS3 mediated tumor suppression through PLIN3-dependent signaling." (PMID 33391508, 2021). "The average tumor expression signals of ACSS3, DHCR14, and SC5D are higher than the expression in normal parental tissues." (PMID 29493120, 2018). "Low ACSS3 expression was positively correlated with tumor stage and Gleason score." (PMID 33391508, 2021). "Similarly, ACSS3 regulated TG and cholesterol contents in tumor cells through PLIN3-dependent signaling." (PMID 33391508, 2021). "Furthermore, the results of oil red staining showed that restoration of ACSS3 expression in C4-2-ENZR tumors significantly reduced LD deposit size in tumor tissues." (PMID 33391508, 2021). "TG and cholesterol assay kits were used to measure TG and cholesterol contents, and Western blotting was used to measure the expression of ACSS3 and PLIN3 in tumor cells." (PMID 33391508, 2021). "Given that ACSS3 promoted PLIN3 protein degradation, we reasoned that PLIN3 is required for ACSS3-mediated tumor suppression." (PMID 33391508, 2021). "To determine the expression of ACSS3, PLIN3, BIP, PERK in tumor tissues, we conducted IHC staining in tumors." (PMID 33391508, 2021). "Next, the expression of ACSS3, PLIN3 and Ki67 in tumor tissues was detected by IHC staining, and TUNEL assays were performed to detect tumor cell apoptosis." (PMID 33391508, 2021).
tumor (continued). "So, we conducted LC/MS to evaluate androgen synthesis in tumor cells, which was the level of testosterone (T) and dihydrotestosterone (DHT) contents in C4-2 cells stably overexpressing ACSS3 and/or knocking down PLIN3." (PMID 33391508, 2021). "C4-2 cells with stable overexpression of ACSS3 and/or knockout of PLIN3 were implanted subcutaneously or into the tail veins of immunodeficient mice to monitor tumor growth and metastasis." (PMID 33391508, 2021). "HNF4A interacts with proteins that are little characterised such as ACSS3, BDH1 and FDXR, and highlights the need for further functional investigations of these proteins in tumour pathogenesis." (PMID 24728830, 2014).
ACSS3 also shares sentences with these, for which no sentence is quoted: bladder cancer (1 paper); Fanconi anemia (1); hepatocellular carcinoma (1); infection (1); leukocyte adhesion deficiency (1); mental disorder (1); ovarian carcinoma (1); pancreatic cancer (1); prostatic intraepithelial neoplasia (1); Type 2 diabetes (1).